S100A11 (S100 calcium binding protein A11)
Description:
Facilitates the differentiation and the cornification of keratinocytes.
Synonyms: MLN70; S100C; HEL-S-43
Tractability: Antibody: its Gene Ontology location is reachable by antibodies, with high confidence. PROTAC: ubiquitination databases record sites on it; its protein half-life has been measured.
Gene: Protein-coding gene on chromosome 1 (152,032,504 to 152,047,907, reverse strand). Ensembl gene ENSG00000163191.
Subcellular location: Cytoplasm; Nucleus
Subcellular location (Human Protein Atlas): Cytosol; Nucleoplasm; Nuclear speckles
Pathways (Reactome):
Immune System: Neutrophil degranulation
Gene Ontology:
Molecular function: cadherin binding involved in cell-cell adhesion; calcium-dependent protein binding; protein binding; protein homodimerization activity; S100 protein binding; calcium ion binding
Biological process: positive regulation of smooth muscle cell migration; negative regulation of cell population proliferation; negative regulation of DNA replication; signal transduction; cell-cell adhesion; regulation of cell population proliferation
Cellular component: adherens junction; cytoplasm; cytosol; extracellular exosome; extracellular region; nuclear speck; nucleoplasm; nucleus; ruffle; secretory granule lumen
Genetic constraint (gnomAD): Loss-of-function variants: 3 observed, 7.15 expected, observed/expected ratio (o/e) 0.42, 90% interval 0.19 to 1.08. That is too few expected variants to judge how well the gene tolerates losing a copy. Missense variants: 93 observed, 124.67 expected, observed/expected ratio (o/e) 0.75, 90% interval 0.63 to 0.89. Synonymous variants: 46 observed, 48.46 expected, observed/expected ratio (o/e) 0.95, 90% interval 0.75 to 1.21.
Homologues: Orthologues: chimpanzee S100A11 (100% identical), guinea pig S100A11 (82% identical), mouse S100a11 (80% identical), rat S100a11 (80% identical), pig S100A11 (76% identical), rat AC117299.1 (70% identical), rat S100a11l1 (70% identical), dog S100A11 (69% identical), zebrafish s100a11 (39% identical). Paralogues in human: S100A1 (36% identical), S100A10 (35% identical), S100A13 (33% identical), S100P (33% identical), S100A12 (31% identical), S100A9 (31% identical), S100B (30% identical), S100A7A (30% identical), S100Z (30% identical), S100A5 (29% identical), S100A2 (28% identical), S100A6 (28% identical), and 9 more.
Diseases named in the same sentence as S100A11 in open-access papers:
S100A11 is named in the same sentence as 122 diseases in open-access papers, as found by Europe PMC text mining. Sharing a sentence is not in itself a finding about the gene and the disease. The quoted sentences say what the papers report.
breast carcinoma (29 papers, 2005 to 2026). "In parallel, high stromal S100-A11 expression is associated with poorer pathological response in a retrospective cohort of early-stage HER2+ breast cancer patients." (PMID 42155177, 2026). "In a retrospective cohort of early-stage HER2+ breast cancer, high stromal S100-A11 expression was associated with residual disease after neoadjuvant therapy and with increased tumour p-STAT3 levels." (PMID 42155177, 2026). "This study aimed to assess the expression, prognosis, and mutation patterns of S100A11 in breast cancer, as well as its interaction network, immune cell infiltration, and immune checkpoints." (PMID 38129538, 2023). "Survival analysis suggested that breast cancer patients with S100A11 mutation had a worse prognosis." (PMID 38129538, 2023). "Our results indicated that S100A9, S100A11 and S100P were associated with worse outcome in all breast cancer patients according to the Kaplan-Meier survival curves and the log-rank P value based on the database." (PMID 28051137, 2017). "However, we did not observe any statistically significant association between S100A11 expression and clinical features, including age, clinical stage, T, N, and M, of breast cancer patients." (PMID 38129538, 2023). "In addition, in prostate and breast cancer, the expression of S100A11 is significantly associated with high pathologic cancer stage, suggesting that S100A11 is involved in cancer development and progression." (PMID 34179021, 2021). "However, the mechanisms underlying the impact of S100A11 on breast cancer development and prognosis remain unclear, and further research is needed to delve into the possible mechanisms." (PMID 38129538, 2023). "Therefore, in conjunction with the immune infiltration, we speculate that S100A11 may be associated with tumor immune escape, potentially affecting the efficacy of immunotherapy and, in turn, the prognosis of breast cancer." (PMID 38129538, 2023). "Recombinant S100-A11 reduced sensitivity to TPD in multiple HER2+ breast cancer cell lines, whereas S100A11 silencing in CAF-200 attenuated the resistance-promoting effect of CAF-conditioned medium in BT-474 and EFM-192A cells." (PMID 42155177, 2026). "This aligns with the findings, which demonstrated that S100A11 promotes tumour growth and metastasis in breast cancer." (PMID 40374593, 2025). "In Cluster 5 (IDC), upregulated genes such as CXCL14, S100A11, CCND1, and AGR2 are linked to breast cancer progression, metastasis, and therapeutic resistance." (PMID 41182757, 2025). "Our research illustrated the critical function of exosomal S100A11 in governing the progression of breast cancer." (PMID 39756316, 2024). "We demonstrated that macrophages underwent LAP to engulf apoptotic cells, released exosomes enriched with S100A11 and absorbed by breast cancer cells." (PMID 39756316, 2024). "Exosomal S100A11 released by LAP-M contributed to progression of breast cancer by means of Akt phosphorylation, indicating of Akt as a promising target to reverse the pro-tumour effect induced by the dying tumour cells." (PMID 39756316, 2024). "At the same time, we also found a strong association between mutations in S100A11 and DFS, DSS, and PFS in breast cancer patients." (PMID 38129538, 2023). "The nomogram containing S100A11 compared favorably with it in predicting 3- and 5-year survival in breast cancer." (PMID 38129538, 2023). "Based on the results of the multifactor Cox regression analysis, we believe that the expression of S100A11 is of significant importance in predicting the prognosis of breast cancer patients." (PMID 38129538, 2023). "S100A11 expression is upregulated in PC, breast cancer, nonsmall cell lung cancer, and colorectal cancer but is decreased in bladder cancer." (PMID 34527585, 2021). "A number of cancers have been reported to involve overexpression of S100A11, including thyroid cancer, colon cancer, pancreatic cancer, and breast cancer." (PMID 33763485, 2021).
breast carcinoma (continued). "Our results indicated that high mRNA expression of S100A8, S100A9, S100A11 and S100P were found to be significantly correlated to worse outcome, while S100A1 and S100A6 were associated with better prognosis in all breast cancer patients." (PMID 28051137, 2017). "We next aimed to evaluate whether exosomal S100A11 could be a predictor of chemotherapy resistance in breast cancer." (PMID 39756316, 2024). "This suggests that breast cancer patients with S100A11 mutations had a worse outcome than those without mutations." (PMID 38129538, 2023). "Therefore, we developed a novel predictive model that combines clinical parameters (age, clinical stage, N, and M) with S100A11 expression to predict the prognosis of breast cancer patients." (PMID 38129538, 2023). "Studies in human tumor cell lines, such as melanoma, pancreatic cancer, breast cancer, and lung cancer, have found that a 19 amino acid peptide from the N-terminus of the S100A11 protein can promote the translocation of apoptosis-inducing factor (AIF) from the cytoplasm to the nucleus." (PMID 34179021, 2021). "Here, our results supported that increased mRNA expression of S100A11 may indicated worse outcome of breast cancer patients." (PMID 28051137, 2017). "Thus the conclusion that S100A9, S100A11 and S100P correlated to worse outcome in breast cancer patients seems plausible, and it’s required to further study the precise prognostic significance of them in breast cancer." (PMID 28051137, 2017). "Gene expression of S100-A11 has specifically been reported as upregulated in basal-type breast cancers compared to non-basal types, which agrees with our findings and S100-A11 [SwissProt: P31949] has been proposed as a diagnostic marker for breast cancer." (PMID 27357824, 2016). "Moreover, we utilized the TCGA database to analyze S100A11-coexpressed genes in breast cancer." (PMID 39756316, 2024). "However, the underlying mechanism of S100A11 in the progression of breast cancer has not yet been elucidated." (PMID 39756316, 2024). "In summary, S100A11 could serve as a biomarker for poor prognosis in breast cancer patients." (PMID 38129538, 2023). "Most breast cancer cells (clusters 0–5) exhibited high levels of hypoxia‐related genes, including HSPA1A, MT2A, S100A11, MALAT1, and UBC." (PMID 39805002, 2025). "The optimized sequence was also applicable to different types of MDA-MB-231 breast cancer cells for the expression of either REIC (left) or a different cargo gene, S100A11 (right)." (PMID 39570532, 2024). "In the breast cancer cell line MCF7, P4 elicits changes in the expression of S100A11, S100A10, calreticulin, VDAC1, SERCA3, and SERCA1, resulting in a barely Ca2+ efflux from the endoplasmic reticulum as well as impaired membrane potential in the mitochondria." (PMID 33076541, 2020). "It is known that S100 proteins are upregulated in basal‐like breast carcinomas and increased expression of S100A11 and S100A14 was correlated with poor outcome in breast cancer." (PMID 30980596, 2019). "For protein-coding genes, SCUBE2 and SDPR were highly expressed in the luminal A subtype, LAPTM5 and YWHAH in the HER2 subtype, and S100A11 and C6ORF211 in the luminal B subtype of breast cancer." (PMID 31801944, 2019). "S100A11 is upregulated in breast cancer, prostate cancer, and nonsmall cell lung cancer, where it promotes tumor metastasis and invasion." (PMID 26106439, 2015). "However, the S100A10 expression level was not highly noticeable in the invasive breast cancers in our in silico analysis; rather S100A11, S100A14, and S100P were markedly elevated in the cancer tissues compared to those in normal breast tissues." (PMID 38595825, 2024).
pancreatic cancer (18 papers, 2015 to 2025). "In addition, S100A11 is considered as a molecular marker for early diagnosis of pancreatic cancer or for screening patients with high-risk lesions that have progressed to pancreatic cancer." (PMID 34804125, 2021). "Their research revealed overexpression of S100A11 in the early stages of pancreatic cancer development, such as in intraductal papillary mucinous neoplasms and pancreatic intraepithelial neoplasia." (PMID 39911323, 2025). "Consistent with the results reported elsewhere, we have also revealed that S100A11 is highly expressed in squamous cell carcinoma, mesothelioma, and pancreatic cancers and plays a crucial role in cancer progression when secreted into extracellular fluid." (PMID 38842658, 2024). "We previously reported that S100A11 secreted from pancreatic cancer cells promotes the proliferation of surrounding fibroblasts and is involved in cancer progression." (PMID 38842658, 2024). "An unfavorable role of S100A11 in pancreatic cancer is also supported by a recent study in human Panc-1 pancreatic cancer cells, where the overexpression of S100A11 led to increased cell proliferation." (PMID 37627239, 2023). "Like S100A2, S100A11 is described to function as either a tumor suppressor, such as in bladder cancer, or a tumor promoter, such as in pancreatic cancer." (PMID 37627239, 2023). "In this respect, S100A11 expression was higher in bulk pancreatic cancer tissues and intraductal papillary mucinous neoplasm than in non-neoplastic pancreatic tissue, and expression decreased with disease progression." (PMID 36872321, 2023). "In pancreatic cancer, the levels of S100A11 were shown to increase during the early stages but decreased during the advanced stages of pancreatic cancer." (PMID 37627239, 2023). "The secretion of its protein, the enzyme regulator S100A11, led to increased cancer cell motility in vitro, and promoted pancreatic cancer cell proliferation in vivo." (PMID 34831349, 2021). "S100A11 levels are elevated in prostate, breast, and pancreatic cancer; however, S100A11 acts as a tumor suppressor in bladder and renal carcinomas." (PMID 34199060, 2021). "Previous studies have shown that S100A11 increases in the early stages of pancreatic cancer, but decreases as cancer progress." (PMID 34804125, 2021). "S100A11 has been shown to play a dual role in tumors, such as inhibiting cancer of the bladder and kidney or promoting cancer of the pancreas." (PMID 34804125, 2021). "Therefore, this study involves the identification of various overexpressed protein members of the S100 protein family, including S100-A4, S100-A6, S100-A8, S100-A9, and S100-A11, to develop a successful multiepitope-based vaccine against pancreatic cancer." (PMID 38976715, 2024). "We hence decided to focus on the S100A11 function in colorectal cancer since we had already reported the S100A11 function in pancreatic cancer, where it acts to fuel the proliferation of cancer-associated fibroblasts (CAFs), yielding enriched cancer fibrosis, a pancreatic cancer trait." (PMID 38842658, 2024). "S100A11 is overexpressed in several cancers, including pancreatic cancer." (PMID 36872321, 2023). "Therefore, targeting S100A11 should be an attractive option for novel treatments of pancreatic cancer." (PMID 35752610, 2022). "Taking these findings together, this study provided new insights into the potential value of S100A11 for treating pancreatic cancer, suggesting that it could be a therapeutic target for PDAC patients." (PMID 35752610, 2022). "It is suggested that S100A11 may regulate PPP in a TKTL1-TKT heterodimer-independent manner, which highlighting clinically a significant association between S100A11 and TKT in pancreatic cancer." (PMID 35752610, 2022). "Furthermore, S100A11 was significantly upregulated in pancreatic cancer tissues compared with the level in normal paracancerous tissues." (PMID 35752610, 2022). "S100A11 is widely overexpressed in pancreatic cancer tissues." (PMID 35752610, 2022).
pancreatic cancer (continued). "Notably, S100A11 was mostly expressed in the nucleus as well as the cytoplasm of pancreatic cancer tissues with strong staining, whereas it was confined to the cytoplasm in normal paracancerous samples with weak intensity." (PMID 35752610, 2022). "S100A11 is overexpressed in several cancers and suggested to act either as tumor suppressor (in bladder and renal carcinoma) or oncogene (in prostate, breast and pancreatic cancer)." (PMID 25940438, 2015). "However, the specific molecular mechanism behind the function of S100A11 in pancreatic cancer remains unclear." (PMID 35752610, 2022). "However, in the pancreatic tumor array, correlations were observed between S100A6 and S100A11 (R = 0.49) and S100A14 (R = 0.45)." (PMID 37627239, 2023). "S100A11 can also promote the proliferation and viability of pancreatic cancer cells by up-regulating the PI3K/AKT signaling pathway, which is considered to be a promising new drug target for targeted therapy of pancreatic cancer." (PMID 34804125, 2021). "Moreover, overexpression of S100A6, S100A10, S100A11, S100A14, and S100A16 may impair the infiltration and cytolytic activity of cytotoxic lymphocytes in pancreatic cancer." (PMID 36982351, 2023).
glioma (14 papers, 2019 to 2025). A benign or malignant brain and spinal cord tumor that arises from glial cells (astrocytes, oligodendrocytes, ependymal cells). "Together, these findings show that S100A11 expression and vascular dysregulation are closely linked to a type of inflammation that promotes glioma tumor progression." (PMID 39744679, 2025). "S100A11 is known to be associated with poor prognosis in glioma patients." (PMID 34148033, 2021). "We tested if S100A11 was associated with glioma stem cell (GSC)." (PMID 31430050, 2019). "Specifically, S100A8 and S100A9 were expressed in myeloid cells, S100A10 and S100A11 in various cell types, especially in glioma tumor cells, and S100A13 and S100A16 in vascular cells." (PMID 39744679, 2025). "Recent studies reported that S100A11 was an oncogene in pancreatic ductal adenocarcinoma 1,2, glioma 3-5, colorectal cancer 6, breast cancer 7, lung cancer 8, thyroid cancer 9, and gastric cancer." (PMID 36605485, 2023). "The tRF-19-R118LOJX affected the glioma cell proliferation, apoptosis, migration and in vitro VM formation via targeted binding and negative regulation of S100A11." (PMID 37864150, 2023). "It has been reported that expression of S100A11, which correlates with glioma pathological grade, promotes the proliferation and tumorigenic capacity of glioma cells, and knockdown of S100A11 expression using shRNA results in the opposite phenotype." (PMID 36040678, 2022). "In our data, S100A10 and S100A11 had the strongest correlation with the immune cell infiltration in glioma." (PMID 34148033, 2021). "S100A11 upregulation can activate the NF-kB pathway and stimulate the invasion and migration of glioma." (PMID 34148033, 2021). "According to this idea, gliomas could be classified according to a hypoxic inflammation linked with S100A9 expression, a perivascular inflammation related to S100A11 expression, and a microglial inflammation associated to S100A13 expression." (PMID 39744679, 2025). "Finally, the involvement of S100A11 expression of pathology progression was performed, comparing primary tumors with recurrences, in our own cohort of recurrent gliomas." (PMID 39744679, 2025). "In contrast, it demonstrates a negative correlation with GMFG, S100A6, and S100A11, all of which are associated with promoting glioma progression." (PMID 38674418, 2024). "The effects of tRF-19-R118LOJX, tRF-19-6SM83OJX and S100A11 on the glioma cell proliferation, migration and in vitro vasculogenic mimicry formation ability were examined by CCK-8 proliferation assay, EdU assay, HoloMonitor cell migration assay and tube formation assay, respectively." (PMID 37864150, 2023). "CGGA database was used to validate the prognostic value of S100A11 in glioma." (PMID 36605485, 2023). "tRF-19-R118LOJX could act as a tumor suppressor in glioma cells and S100A11 was a direct target of tRF-19-R118LOJX in regulating glioma development." (PMID 37864150, 2023). "Whether CASP4 (Caspase-4) and S100A11 act synergistically in gliomas remains unclear." (PMID 35118063, 2021). "In our previous study, we developed an S100 family-based prognostic signature consisting of five genes of S100A11, S100A16, S100B, S100PBP and S100A13 for glioma patients." (PMID 37151881, 2023). "Overexpression of S100A11 promoted GBM cell growth, epithelial-mesenchymal transition, migration, invasion, and generation of glioma stem cells." (PMID 37864150, 2023). "In terms of mechanism, the risk-score signature was positively associated with the expression of inflammatory molecules such as S100A11 and CASP4 in glioma." (PMID 35118063, 2021). "Firstly, the S100A11, S100A16, and S100B expression levels were significantly upregulated in glioma tissues than in normal controls from GEPIA database." (PMID 34712325, 2021). "Overexpression of S100A11 promoted GBM cell growth, epithelial‐mesenchymal transition (EMT), migration, invasion and generation of glioma stem cells (GSCs), whereas its knockdown inhibited these activities." (PMID 31430050, 2019).